QTRT1 (queuine tRNA-ribosyltransferase catalytic subunit 1)
Description:
Catalytic subunit of the queuine tRNA-ribosyltransferase (TGT) that catalyzes the base-exchange of a guanine (G) residue with queuine (Q) at position 34 (anticodon wobble position) in tRNAs with GU(N) anticodons (tRNA-Asp, -Asn, -His and -Tyr), resulting in the hypermodified nucleoside queuosine (7-(((4,5-cis-dihydroxy-2-cyclopenten-1-yl)amino)methyl)-7-deazaguanosine). Catalysis occurs through a double-displacement mechanism. The nucleophile active site attacks the C1' of nucleotide 34 to detach the guanine base from the RNA, forming a covalent enzyme-RNA intermediate. The proton acceptor active site deprotonates the incoming queuine, allowing a nucleophilic attack on the C1' of the ribose to form the product (By similarity). Modification of cytoplasmic tRNAs with queuosine controls the elongation speed of cognate codons, thereby ensuring the correct folding of nascent proteins to maintain proteome integrity.
Synonyms: TGT; TGUT; FP3235
Tractability: Small molecule: a structure with a bound ligand is known. Antibody: UniProt places it where antibodies can reach, with medium confidence. PROTAC: ubiquitination databases record sites on it; its protein half-life has been measured; a small molecule that binds it is known.
Target class: Enzyme; Transferase
Gene: Protein-coding gene on chromosome 19 (10,701,430 to 10,713,437, forward strand). Ensembl gene ENSG00000213339.
Subcellular location: Cytoplasm; Mitochondrion outer membrane
Subcellular location (Human Protein Atlas): Mitochondria
Pathways (Reactome):
Metabolism of RNA: tRNA modification in the nucleus and cytosol
Gene Ontology:
Molecular function: protein binding; tRNA-guanosine(34) queuine transglycosylase activity
Biological process: tRNA wobble guanine modification; tRNA modification
Cellular component: mitochondrion; transferase complex; tRNA-guanine transglycosylase complex; cytoplasm; mitochondrial outer membrane; cytoplasmic side of mitochondrial outer membrane; nucleus; protein-containing complex
Genetic constraint (gnomAD): Loss-of-function variants: 41 observed, 44.11 expected, observed/expected ratio (o/e) 0.93, 90% interval 0.72 to 1.21. The upper end of that interval is the gene's LOEUF score, 1.21, which puts it in group 5 of 6, group 1 being the genes least tolerant of losing a copy. Missense variants: 542 observed, 577.52 expected, observed/expected ratio (o/e) 0.94, 90% interval 0.87 to 1.01. Synonymous variants: 226 observed, 233.2 expected, observed/expected ratio (o/e) 0.97, 90% interval 0.87 to 1.08.
Homologues: Orthologues: chimpanzee QTRT1 (100% identical), macaque QTRT1 (98% identical), pig QTRT1 (93% identical), guinea pig QTRT1 (90% identical), mouse Qtrt1 (87% identical), rat Qtrt1 (85% identical), rabbit QTRT1 (80% identical), tropical clawed frog qtrt1 (72% identical), zebrafish qtrt1 (71% identical), Drosophila melanogaster Tgt (57% identical), Caenorhabditis elegans tgt-1 (51% identical). Paralogues in human: QTRT2 (22% identical).
Diseases named in the same sentence as QTRT1 in open-access papers:
QTRT1 is named in the same sentence as 13 diseases in open-access papers, as found by Europe PMC text mining. Sharing a sentence is not in itself a finding about the gene and the disease. The quoted sentences say what the papers report.
atherosclerosis (2 papers, 2022 to 2024). A disease characterized by the build-up of fatty material and calcium deposition in the arterial wall resulting in partial or complete occlusion of the arterial lumen. "QTRT1 mutations influenced EOCAD risk through DNL dysregulation and accelerated atherosclerosis." (PMID 36060302, 2022).
psoriasis (2 papers, 2023 to 2024). An autoimmune condition characterized by red, well-delineated plaques with silvery scales that are usually on the extensor surfaces and scalp. "Rs892085 is located in an intron of the QTRT1 gene, in close proximity to the ILF3 and CARM1 genes, and has been associated with psoriasis, with the risk allele A." (PMID 38898675, 2024). "However, also in this case interesting examples of co-occurrences may be found, often involving genes known to be associated with Psoriasis, such as QTRT1, as well as genes related to other diseases, e.g. ERF, implied in complex craniosynostosis, and ISOC2, biomarker of Osteoarthrosis Deformans." (PMID 37021928, 2023).
breast carcinoma (1 paper, 2020). "Our data demonstrated that the bacterial species level between WT and QTRT1-deficient groups had differences in alpha and beta diversities, which are potentially associated with breast cancer status and progression." (PMID 32182756, 2020). "We found that QTRT1 deficiency in human breast cancer cells could change the functions of regulation genes, which are critical in cell proliferation, tight junction formation, and migration in human breast cancer cells in vitro and a breast tumor mouse model in vivo." (PMID 32182756, 2020). "To confirm the role of QTRT1 in breast cancer cells, we knockdown QTRT1 in the MDA-MB-231 breast cancer cells." (PMID 32182756, 2020). "In the current study, we demonstrated that QTRT1 plays a crucial role in breast cancer cell proliferation and growth both in vitro and in vivo." (PMID 32182756, 2020). "We identified the functions of the QTRT1 gene in regulating critical genes in cell proliferation, tight junction, and migration with human breast cancer cells and a breast tumor mouse model." (PMID 32182756, 2020). "The proliferation and collective migration of QTRT1-KO MCF7 breast cancer cells were markedly suppressed, compared with its parent cells." (PMID 32182756, 2020). "To confirm the role of QTRT1 in breast cancer cells, we further knockdown QTRT1 in the MDA-MB-231 breast cancer cells." (PMID 32182756, 2020). "The CD68-positive and CD-11b-positive inflammation-related cells were immunostained in the tumors from nude mice injected with WT or QTRT1-KO breast cancer cells, indicating an immune response inside the tumors." (PMID 32182756, 2020). "To elucidate the mechanism of how suppressed QTRT1 expression leads to altered proliferation and migration of breast cancer cells, we investigated the expression of markers of cell adhesion proteins, including β-catenin and E-cadherin." (PMID 32182756, 2020). "Using the WT and QTRT1-KD MDA-MB-231 breast cancer cells, we showed the QTRT1-induced alterations of β-catenin and claudin-5." (PMID 32182756, 2020). "Conclusively, we have demonstrated the important functions of QTRT1/Q-tRNA modification in regulating development of breast cancer.." (PMID 32182756, 2020). "The suppression of cell proliferation and migration of QTRT1 deletion were confirmed with the knockdown of QTRT1 in MDA-MB-231 breast cancer cells." (PMID 32182756, 2020). "To investigate the role of QTRT1 in the migration of breast cancer cells, we investigated the wound healing ability of these cells." (PMID 32182756, 2020). "To investigate the effects of QTRT1 on breast cancer tumor growth, we used the Double Nickase Plasmid to suppress the expression of QTRT1 in MCF7 cells." (PMID 32182756, 2020). "We generated single clones of complete QTRT1-KO in human breast cancer MCF7 cells." (PMID 32182756, 2020). "Knockout or reduction of QTRT1 could significantly suppress the proliferation and migration of breast cancer cells." (PMID 32182756, 2020). "The breast cancer cell injected groups had significantly different variations between WT MCF7 and QTRT1-KO groups (p = 0.0028)." (PMID 32182756, 2020). "Immunofluorescence staining further showed increased β-catenin in tumors from QTRT1-KO injected mice, compared to that in WT MCF7 breast cancer cells." (PMID 32182756, 2020).
dyslipidemia (1 paper, 2024).
lung adenocarcinoma (1 paper, 2021). A carcinoma that arises from the lung and is characterized by the presence of malignant glandular epithelial cells. "In addition, queuine tRNA-ribosyltransferase (QTRT1), the enzyme that catalyzes the hypermodification of queuosine using 7-aminomethyl-7-carbaguanine, is highly expressed in lung adenocarcinoma (LUAD), and has been identified as a risk factor for the progression of LUAD." (PMID 34944874, 2021).
lung carcinoma (1 paper, 2023). "Conversely, a significant increase in QTRT1 expression and a striking down-regulation in its methylation was also found in lung cancer." (PMID 37719021, 2023).
multiple sclerosis (1 paper, 2021). A progressive autoimmune disorder affecting the central nervous system resulting in demyelination. "Of note, queuosine hypomodification has been reported in several cancers and in multiple sclerosis via reduced activity of tRNA guanine transglycosylase (TRT) or via promoter methylation of the genes coding for the TRT subunits (QTRT1 and QTRT2)." (PMID 34539450, 2021).
cancer (3 papers, 2020 to 2024). A tumor composed of atypical neoplastic, often pleomorphic cells that invade other tissues. "The knockout of QTRT1 resulted in the loss of aggressiveness of cancer cells both in vitro and in vivo." (PMID 32182756, 2020).
tumor (1 paper, 2020). "Similarly, our findings indicate that the QTRT1-associated altered microbiome and microenvironment may contribute to tumor growth." (PMID 32182756, 2020). "The suppression of tumor growth and alteration of TJ proteins in the tumors were also found in the QTRT1 knockdown MDA-MB-231 cells, using the xenograft nude mouse model." (PMID 32182756, 2020). "Suppressed cell proliferation in QTRT1 knockout contributed to marked reduction of the tumor growth, number, volume, and weight." (PMID 32182756, 2020). "The impacts of QTRT1 deletion or reduction on cell proliferation and migration in vitro were evaluated using cell culture, while the regulations on tumor growth in vivo were evaluated using a xenograft BALB/c nude mouse model." (PMID 32182756, 2020). "Our findings provide new insights into manipulating QTRT1 as a potential gene in controlling tumor growth and development through the gut–microbiome–tumor axis." (PMID 32182756, 2020). "We found that the total tumor number, tumor volume, and weight were significantly reduced in mice injected with QTRT1-KO MCF7 cells compared to the WT cells (p < 0.01)." (PMID 32182756, 2020). "In the future, studies are also needed to understand the mechanisms of how QTRT1 interacts within TJ proteins to influence cell proliferation and tumor growth." (PMID 32182756, 2020). "The relative abundance of bacteria in tumor induced from WT cells was significantly higher than that of QTRT1-KO cells using both EUB338 and Bfi826 probes (p < 0.01 and p < 0.05, respectively)." (PMID 32182756, 2020). "The bacteria’s existence in the tumors was confirmed with the tumor samples from the mice challenged with QTRT1-KD and WT MDA-MB-231 cells." (PMID 32182756, 2020). "The knockout of QTRT1 in MCF7 cells could impact the cell proliferation ability, which influences the microenvironment of the tumors and could feedback to affect the bacterial multiplication in the tumor." (PMID 32182756, 2020).
QTRT1 also shares sentences with these, for which no sentence is quoted: breast tumor (1 paper); coronary artery disease (1); craniosynostosis (1); Hypercholesterolemia (1).